CTSG (cathepsin G)
Diseases named in the same sentence as CTSG in open-access papers (continued):
Sharing a sentence is not in itself a finding about the gene and the disease.
renal carcinoma (2 papers, 2017 to 2021). A carcinoma arising from the epithelium of the renal parenchyma or the renal pelvis. "CACNA1D (Voltage-dependent L-type calcium channel subunit alpha-1D) is lowly expressed in RCC, and the expression level of CASP9 (Caspase-9) is altered in RCC by rs12124078 SNP, while CTSG (Cathepsin G) inhibition enhances apoptosis in human renal carcinoma (Caki) cells." (PMID 33573278, 2021). "Therefore, we investigated whether inhibition of cathepsin G could have anti-cancer effects in human renal carcinoma Caki cells." (PMID 29290980, 2017).
Sjögren’s syndrome (2 papers, 2021 to 2025). "The identification of elevated levels of proteases such as neutrophil elastase, cathepsin G, myeloblastin, and trypsin exclusively in saliva samples from Sjögren’s syndrome patients indicates that the mechanisms of neutrophil and immune cell degranulation play a significant role in the disease." (PMID 41301757, 2025). "Garreto and colleagues also revealed a significant increase in the levels of Matrix Metalloproteinase-9 (MMP9), Neutrophil Elastase (ELANE), Cathepsin G (CTSG), and Myeloblastin (PRTN3) in the saliva of patients with Sjögren’s syndrome compared to healthy controls." (PMID 41301757, 2025).
abscess (1 paper, 2023). An inflammatory process characterized by the accumulation of pus within a newly formed tissue cavity which is the result of a bacterial, fungal, or parasitic infection or the presence of a foreign body. "In a recent analysis of the proteomic components of different abscess regions, neutrophil surface markers and multiple neutrophil-specific antimicrobial factors—including CTSG and ELANE—were detected in the abscess at the host–pathogen interface." (PMID 37118737, 2023).
acute pancreatitis (1 paper, 2019). An acute inflammatory process that leads to necrosis of the pancreatic parenchyma. "In CTSG−/− mice a transient decrease of neutrophil infiltration into the pancreas and lungs was found during acute pancreatitis while the disease severity remained largely unchanged." (PMID 31727956, 2019). "In view of the different interactions of CTSG under inflammatory conditions we investigated whether this serine protease also exerts effects on acute pancreatitis using a knockout mouse model for CTSG." (PMID 31727956, 2019). "To investigate whether depletion of CTSG alters the disease severity in acute pancreatitis mice we induced acute experimental pancreatitis using the caerulein-model." (PMID 31727956, 2019). "Although CTSG reduces invasion of neutophil granulocytes this effect was not sufficient to decrease the severity of acute pancreatitis, giving it an inferior role to neutrophil granulocyte enzymes such as PNM elastase." (PMID 31727956, 2019). "Local pancreatic injury, determined by histological damage, consisting of vacuolization, necrosis, and inflammatory cell infiltration, increased during acute pancreatitis but was independent of the presence of CTSG, as no significant changes were observed between the groups." (PMID 31727956, 2019).
allergic rhinitis (1 paper, 2011). Inflammation of the nasal mucous membranes caused by an IgE-mediated response to external allergens. "PU.1 has been also shown to be a key regulator of transcription of the cathepsin G gene, which has been associated to allergic rhinitis previously." (PMID 21625490, 2011).
aortic aneurysm (1 paper, 2021). A ruptured aneurysm located in the wall of the proximal portion of the descending aorta proceeding from the arch of the aorta. "CTSG (cathepsin G) is a protein coding gene plays important roles in aortic aneurysms." (PMID 34218797, 2021).
autoimmune myocarditis (1 paper, 2023). Autoimmune myocarditis is an autoimmune disease that affects the heart. "For example, linagliptin has been reported to effectively inhibit myocardial inflammation by increasing serpina3n activity and repressing cathepsin G activity in mice with experimental autoimmune myocarditis, suggesting that serpina3n exerts an anti-inflammatory role." (PMID 37594700, 2023).
breast tumors (1 paper, 2022). "CTSG can also activate pro-MMP-9 to cut and release active transforming growth factor β (TGF-β), MMP-13, and RANKL at the tumor-bone interface of osteolytic lesions induced by breast tumors." (PMID 35935989, 2022).
Cerebral ischemia (1 paper, 2022). Restriction of arterial blood supply to the brain associated with insufficient oxygenation to support the metabolic requirements of the tissue. "Neutrophils are involved in brain injury after cerebral ischemia by releasing proteases, including elastase, metalloproteinase (MMP9) and cathepsin G, as well as reactive oxygen species, nitrogen species and inflammatory IL-1β." (PMID 36818726, 2022).
chronic rhinosinusitis (1 paper, 2024). Chronic form of sinusitis. "In this regard, our proteomic analysis identified neutrophil elastase, cathepsin G. In a recent study, both eosinophilic and neutrophilic extracellular traps were identified to play a significant role in chronic rhinosinusitis." (PMID 39596842, 2024).
diffuse large B-cell lymphoma (1 paper, 2023). "Cathepsin G (CTSG) overexpression is associated with poor diffuse large B-cell lymphoma survival." (PMID 37705968, 2023).
Dupuytren's disease (1 paper, 2021). "Cathepsins B and D are localized to OCT4+ endothelium as well as the smooth muscle layer of microvessels within Dupuytren's disease and cathepsin G is predominantly localized to OCT4+/chymase+ mast cells within the stroma." (PMID 34409065, 2021). "Expression of the cysteine protease cathepsin B, the aspartyl protease cathepsin D and the serine protease cathepsin G are expressed by ESC-like cells in IH, and microvessels in Dupuytren's disease and keloid disorder." (PMID 34409065, 2021).
fatty liver (1 paper, 2022). "Therefore, increased abundance of 0-Gran-Wfdc17, elevated levels of neutrophil serine proteases (NE, PRTN3 and Cathepsin G), and upregulated genes enriched in NETs formation are involved in the aggravation of fatty liver caused by loss of ApoA4." (PMID 36426356, 2022).
Granuloma (1 paper, 2024). A compact, organized collection of mature mononuclear phagocytes, which may be but is not necessarily accompanied by accessory features such as necrosis. "For instance, the granulomas that form after mycobacterium tuberculosis infects the lung are rich in Cathepsin G." (PMID 39080685, 2024).
Hepatic fibrosis (1 paper, 2025). The presence of excessive fibrous connective tissue in the liver. "Therefore, we investigated whether cathepsin G is involved in hepatic fibrosis in MASH and is controlled by Serpina3k." (PMID 40744994, 2025).
Hypertension (1 paper, 2017). The presence of chronic increased pressure in the systemic arterial system. "In addition, we speculated whether proteins CTSG and TGF-β1 would become new hypertension treatment targets." (PMID 29201909, 2017).
Hypoglycemia (1 paper, 2025). A decreased concentration of glucose in the blood. "Following hypoglycemia, transient changes from baseline occurred in DKK1, cathepsin A, cathepsin G, cathepsin H, cathepsin S, cathepsin Z, parathyroid hormone (PTH), Sphingosine kinase 1 and 2 (SPK1/2), and interleukin-1 beta (IL1 beta) over the post-hypoglycaemia time course." (PMID 41373586, 2025).
idiopathic pulmonary fibrosis (1 paper, 2007). Idiopathic pulmonary fibrosis (IPF) is a nonneoplastic pulmonary disease that is characterized by the formation of scar tissue within the lungs in the absence of any known cause. "For example, in systemic sclerosis patients with pulmonary fibrosis or idiopathic pulmonary fibrosis (IPF) patients, concentrations of thrombin and/or cathepsin G in bronchoalveolar lavage fluid are much higher than those in healthy controls." (PMID 17433115, 2007).
infantile hemangioma (1 paper, 2017). "To further characterize the cathepsin D+ (red) and cathepsin G+ (red) cells, we performed co-staining with tryptase, as we have reported in infantile hemangioma." (PMID 28775982, 2017). "However, cathepsin D is localized only to the CSC subpopulation within the TNs, while cathepsin G is localized exclusively to the tryptase+ phenotypic mast cells within the peri-tumoral stroma, similar to the finding in infantile hemangioma." (PMID 28775982, 2017).
Kawasaki disease (1 paper, 2022). A rare inflammatory disease characterized by an acute febrile, systemic, self-limiting, medium-vessel vasculitis primarily affecting children. "Cathepsin G (CTSG) is an important factor leading to inflammation of Kawasaki disease and is an antibacterial protein present in neutrophils." (PMID 35990842, 2022). "The experimental results suggested that aspirin can treat Kawasaki disease by regulating inflammatory response by acting on CTSG, FGF1, and ELANE." (PMID 35990842, 2022). "In the treatment of Kawasaki disease, aspirin may regulate inflammatory response and vascular remodeling through CTSG, ELANE, and FGF1." (PMID 35990842, 2022). "We find that aspirin treats Kawasaki disease through CTSG, ELANE, and FGF1." (PMID 35990842, 2022). "Molecular docking indicated that aspirin had close binding sites to CTSG, Elane, and FGF1 in Kawasaki disease." (PMID 35990842, 2022). "In the study, 13 core targets (such as CTSG, ELANE, and FGF1) highly related to Kawasaki disease and aspirin were identified by bioinformatics method." (PMID 35990842, 2022). "In conclusion, bioinformatics analysis and computer simulation research indicated that CTSG, ELANE, and FGF1 were key targets of aspirin in Kawasaki disease." (PMID 35990842, 2022).
kidney tumor (1 paper, 2015). "Likewise, we showed that high levels of a neutrophil gene network including CTSG (Cathepsin G, a component of the azurophilic granules of neutrophils) are associated with poor survival of kidney tumor patients." (PMID 26398410, 2015).
Klebsiella pneumonia (1 paper, 2017). An pneumonia caused by infection with Klebsiella. "gga-miR-138 was significantly downregulated in the CM group compared to the level in the NC group and may inhibit inflammation by enhancing CTSG, which has broad-spectrum antibiotic properties against Staphylococcus aureus, Klebsiella pneumonia and Escherichia coli (35, –, 37)." (PMID 27795362, 2017).
mycoplasma infection (1 paper, 2015). "This argues against a major, non-redundant role for Dppi (or for neutrophil serine proteases like cathepsin G and elastase that depend on Dppi for activation) in recruitment or migration of neutrophils in response to mycoplasma infection." (PMID 25938594, 2015).
myocardial infarct (1 paper, 2019). "The CTSG N125S G allele has been associated with elevated plasma fibrinogen levels in myocardial infarct patients." (PMID 31647805, 2019).
Neonatal sepsis (1 paper, 2025). Systemic inflammatory response to infection in newborn babies. "Lastly, we identified genes that reliably distinguished neonatal sepsis endotypes, with the top two being cathepsin G (CTSG) and matrix metalloprotease 8 (MMP8)." (PMID 40655143, 2025).
neuromyelitis optica (1 paper, 2018). A rare inflammatory disease of the central nervous system characterized mainly by attacks of uni- or bilateral optic neuritis (ON) and acute myelitis. "In a study investigating the effects of neutrophils in a mouse model of neuromyelitis optica, intracerebral injection of inhibitors of neutrophil elastase and cathepsin G, as well as intraperitoneal injection of neutrophil elastase inhibitor alone, reduced neuromyelitis optica brain lesions." (PMID 30149799, 2018).
neutropenia (1 paper, 2024). A decrease in the number of neutrophils found in the blood. "As p22-phox, ELANE, and cathepsin G are primarily expressed in granulocytes, analyses of these proteins may also be useful in identifying patients with other diseases that are accompanied by neutropenia." (PMID 39453496, 2024).
pancreatitis (1 paper, 2019). Inflammation of the pancreas. "CTSG is involved in pancreatic neutrophil infiltration during pancreatitis, albeit to a lesser degree than the related neutrophil (PMN) elastase." (PMID 31727956, 2019). "In CTSG−/− mice and corresponding controls acute experimental pancreatitis was induced by serial caerulein injections." (PMID 31727956, 2019). "The aim of this study was to investigate the role of CTSG in pancreatitis." (PMID 31727956, 2019). "Moreover, protease activation in acinar cells, a hallmark of early pancreatitis, was independent of CTSG." (PMID 31727956, 2019). "In conclusion, our results indicate that the absence of cathepsin G leads to a transient reduction in neutrophil granulocyte invasion but leaves pancreatitis severity largely unaffected." (PMID 31727956, 2019).
paracoccidioidomycosis (1 paper, 2012). A systemic fungal infection caused by Paracoccidioides brasiliensis that is most often seen in immunocompromised patients. "In mice, after infection by Paracoccidioides brasiliensis (a fungus that causes Paracoccidioidomycosis, a systemic mycosis), a very high protein diet was associated with a greater increase in spleen and liver Cathepsin G mRNA than a low protein diet." (PMID 22844403, 2012).
peritonitis (1 paper, 2019). Inflammation of the peritoneum (tissue that lines the abdominal wall and covers most of the organs in the abdomen). "Mice deficient in both neutrophil elastase and cathepsin G have been investigated in a previous study, that showed a normal recruitment of neutrophils to the site of inflammation upon induction of sterile peritonitis." (PMID 31727956, 2019).
primary immunodeficiency (1 paper, 2021). "In particular, we detected that ZAP70 was enriched in primary immunodeficiency, TNFRSF4, and CXCL5 were enriched in cytokine-cytokine receptor interaction, CTSG was enriched in the renin-angiotensin system, and the CHRM2 and CTSG were enriched in neuroactive ligand-receptor interaction." (PMID 34133324, 2021).
prion disease (1 paper, 2019). A transmissible disease that is caused by a protein that is able to induce abnormal folding of normal cellular proteins, leading to characteristic spongiform brain changes, which are associated with neuronal loss without an inflammatory response. "The protein antagonizes the activity of neutrophil cathepsin G and mast cell chymase and has been implicated in neuroinflammation, neurodegeneration, and other types of brain conditions such as human prion diseases." (PMID 31447881, 2019).
prostate carcinoma (1 paper, 2015). A carcinoma that arises from epithelial cells of the prostate gland. "In the present study, we found that IL–20 directly induced the cleavage of RANKL from the surface membrane of prostate cancer cells by upregulating cathepsin G expression." (PMID 26440411, 2015). "In vitro, IL–20 upregulated N-cadherin, STAT3, vimentin, fibronectin, RANKL, cathepsin G, and cathepsin K, and increased the migration and colony formation of prostate cancer cells via activated p38, ERK1/2, AKT, and NF-κB signals in PC–3 cells." (PMID 26440411, 2015). "Based on our in vitro data, we speculated that IL–20 might promote osteoclastogenesis by regulating sRANKL and cathepsin G expression in prostate cancer cells." (PMID 26440411, 2015).
psoriatic arthritis (1 paper, 2023). Joint inflammation associated with psoriasis. "This retrospective case-control study examined the relationship between the serum and synovial levels of cathepsin G (CatG) and cathepsin K (CatK) in patients with psoriatic arthritis (PsA) and their association with disease activity." (PMID 37892071, 2023).
pustular psoriasis (1 paper, 2023). "Other genes involved in pustular psoriasis are SERPINA1 and SERPINA3 (serine protease inhibitors that inhibit cathepsin G, neutrophil elastase, and proteinase 3), TNIP1 and IL1RN." (PMID 37628670, 2023).
spondyloarthritis (1 paper, 2020). "Recent proteomic analysis of SF from RA patients and spondyloarthritis (SpA) patients identified elevated levels of many neutrophil proteins in RA SF, including MPO, cathepsin G, annexin-A1 and NGAL." (PMID 33469455, 2020).
squamous cell carcinoma (1 paper, 2023). A carcinoma arising from squamous epithelial cells. "Additionally, weaker positive effects were observed for cathepsin H levels and the risk of squamous cell carcinomas, and cathepsin G levels and the risk of adenocarcinoma, respectively, only by the IVW method (p = 0.032, OR = 1.053, 95% CI = 1.005–1.104; p = 0.041, OR = 1.095, 95% CI = 1.004–1.195)." (PMID 37805623, 2023).
thrombosis (1 paper, 2022). "We also made use of the same experimental animal thrombosis model, applied before in our air pollutant studies, to validate the impact of infused cathepsin G and elastase on peripheral thrombogenicity, upon inflicting mild vascular injury." (PMID 35054930, 2022). "In the mouse thrombosis model, cathepsin G and elastase amplified mild thrombogenicity at blood concentrations that activated platelets in vitro." (PMID 35054930, 2022).
triple-negative breast carcinoma (1 paper, 2025). An invasive breast carcinoma which is negative for expression of estrogen receptor (ER), progesterone receptor (PR), and human epidermal growth factor receptor 2 (HER2). "CTSG has also been implicated in triple-negative breast cancer (TNBC), where it is overexpressed and correlated with a poor prognosis." (PMID 39869563, 2025).
ulcers (1 paper, 2021). "For example, the major enzymes from neutrophils, human neutrophil elastase (HNE), and cathepsin G have been reported as early-stage warning markers for non-healing ulcers." (PMID 34227939, 2021).
vascular occlusive diseases (1 paper, 2013). "Additional experiments are needed to determine the potential benefits and risks of cathepsin G inhibitors in animal models of vascular occlusive diseases." (PMID 23940756, 2013).
visceral leishmaniasis (1 paper, 2023). A severe form of leishmaniasis characterized by irregular bouts of fever, substantial weight loss, swelling of the spleen and liver, and anemia (which may be serious). "Of interest, among the Leishmania-upregulated Ago1-dependent proteins, Cathepsin G (CTSG), has been shown to be significantly enriched at the late chronic phase of visceral leishmaniasis in mice." (PMID 38098491, 2023).